LRP1B (LDL receptor related protein 1B)
Diseases named in the same sentence as LRP1B in open-access papers (continued):
Sharing a sentence is not in itself a finding about the gene and the disease.
cancer (continued). "LRP1B, or Low-Density Lipoprotein Receptor-related protein 1B, is a frequently altered gene in multiple cancer types, but its exact role remains unclear." (PMID 38769532, 2024). "While directly modifying the LRP1B gene in cancer cells may present challenges, targeting the molecules influenced by LRP1B could offer more suitable avenues for therapeutic intervention." (PMID 37511044, 2023). "Moreover, disruption of this gene has been reported in several types of cancer, and the LRP1B protein is also found at the cell surface receptor involved in receptor-mediated endocytosis in the fetal brain." (PMID 38019868, 2023). "The ability to edit the LRP1B gene and effectively impact protein expression may be crucial to unravel the role of LRP1B in cancer biology and to identify new players." (PMID 37511044, 2023). "Despite considerable research, the precise role of LRP1B in cancer has yet to be fully elucidated." (PMID 37511044, 2023). "Accordingly, LRP1B mutations are associated with favorable outcomes in response to immune checkpoint inhibitors (ICI) across multiple cancer types, similar to the higher TMB cancer outcomes." (PMID 37511044, 2023). "Despite all the studies pointing towards LRP1B as a prognosis and/or predictive response biomarker and as a possible target in cancer treatment, the full impact of LRP1B alterations at gene and protein level on cancer biology remains unknown." (PMID 37511044, 2023). "The remaining most frequent mutated cancer driver genes found in early-stage samples (KMT2C, ALK, BRCA2, GRM, ATM, and BRCA1) were not among those found to be the most frequently shared in late-stage samples (MUC16, CSMD3, KNT2C, NF1, LRP1B, SPEN, and TRRAP)." (PMID 37446001, 2023). "LRP1B was the highest frequency mutated gene of TMB-high patients in our study and also had been validated to be associated with a high level of TMB in various types of cancer in previous studies." (PMID 36686739, 2022). "Functional studies have confirmed that LRP1B expression in cancer cells could reduce in vitro cell proliferation and migration abilities, and also suppress in vivo tumorigenicity in mouse models." (PMID 36243813, 2022). "The following most altered cancer genes were LRP1B (26%), PIK3CA (24%), CDKN2A (24%), PTPRD (15%), RB1 (13%), PDE4DIP (13%), PCLO (11%), KRAS (11%), FAT1 (10%), and RELN (10%), and these results partially overlap with the most altered genes depicted in the experimental cohort." (PMID 35330454, 2022). "Importantly, in association with LRP1B mutation, higher TMB and improved outcomes in patients treated by immune checkpoint inhibitors across different cancer types have been described." (PMID 34680332, 2021). "For example, FHIT, CSMD1, and LRP1B have been reported in cancer and lesions." (PMID 33810183, 2021). "Knowledge on LRP1B has been closely related to its possible involvement in cancer." (PMID 34577535, 2021). "LRP1B is among the most altered genes in human cancer overall." (PMID 34577535, 2021). "LRP1B, a close homolog of LRP1, is among the top 10 significantly mutated genes in human cancer." (PMID 32850302, 2020).
cancer (continued). "The recombinant Lrp1b construct represents a valuable tool to unravel the largely unknown physiological role of LRP1B and its potential functions in cancer pathogenesis." (PMID 27626682, 2016). "Additionally, a large study of somatic copy-number alterations and human cancers identified LRP1B deletions as a significant finding." (PMID 25945796, 2015). "LRP1B belongs to the LDL receptor family and its mutations are often found in human cancers." (PMID 25296178, 2014). "Of note, the 5 shared candidate cancer genes of tumors 05 and 09 (Pten, Fas, Esr1, Abl2, Lrp1b) were independently obtained in both tumors with similar average read frequencies, confirming the robustness of our sequencing method to identify clonal expansion of insertions." (PMID 23940809, 2013). "To determine whether the internal deletion of exons in the Lrp1b gene is relevant to human cancer, we examined 770 human cancer cell lines for which we had previously generated high-resolution aCGH (Affymetrix SNP6) data." (PMID 20942901, 2010). "Additionally, LRP1B may regulate the malignant behavior of cancer cells through the Hh signaling pathway." (PMID 40170839, 2025). "Additionally, LRP1B is among the most frequently altered genes in human cancer overall." (PMID 38769532, 2024). "However, recent advances in gene editing technologies, such as CRISPR/Cas9, have provided a new opportunity to manipulate LRP1B gene and protein expression in cells, which may enable the investigation of LRP1B’s functional role in cancer." (PMID 37511044, 2023). "Therefore, LRP1B expression and function in cancer remains to be fully unveiled." (PMID 34577535, 2021). "To explore the dysregulation of LRP1B, we analyzed CRC sample data and observed significant differences in expression levels between cancer tissues and cancer-adjacent normal tissues from public datasets of GEO and TCGA." (PMID 40170839, 2025). "LRP1B’s correlation with TMB and immunotherapy efficacy has been confirmed in multiple cancers, including lung cancer." (PMID 39727930, 2024). "SCIN, LRP1B, CPNE3, TICRR, and PPP1R7 are connected to cancer cell invasion, migration, proliferation, and apoptosis." (PMID 37628788, 2023). "Four cancer driver genes, namely KMT2D, LRP1B, TRRAP, and FLNA, were identified in the 20 most frequently mutated gene sets." (PMID 37373553, 2023).
cancer (continued). "For example the low-density lipoprotein receptor-related protein 1B (Lrp1b), which is downregulated in CRC, can suppress the growth and migration of cancer cells via inhibiting the interaction between Dvl2 and the Axin and hence the Wnt/β-catenin signaling." (PMID 33585487, 2021). "Based on host genome integration frequencies, we found previously reported integration sites in cancer for genes like FHIT, CSMD1, and LRP1B and putatively many new ones such as those exemplified in CSMD3, ROBO2, and SETD3." (PMID 33810183, 2021). "LRP1B is a member of the low-density lipoprotein receptor family and a putative TSG that is frequently inactivated to promote cell migration and invasion in various human cancers." (PMID 37377752, 2023). "LRP1B and KMT2C were subclonal in two primary cancers (UCEC and BRCA, UCEC and LUNG, respectively)." (PMID 36497297, 2022). "Despite the frequency of LRP1B dysfunction in cancer overall, there is still a lack of information on how this affects its expression and/or functional role." (PMID 34577535, 2021). "Interestingly, TCI revealed functional impact of certain SGAs with very high alteration frequencies, such as TTN, CSMD3, MUC16, RYR2, LRP1B, and ZFHX4, whose roles in cancer development remain controversial." (PMID 31276486, 2019). "Due to the abundance of CpG islands in LRP1 gene promoter and frequent hypermethylation of LRP1B, another member of the LRP family, in various cancer types, it could be possible that LRP1 gene methylation might regulate its expression." (PMID 29507659, 2018). "Secondly, the biomarker role of LRP1B in ICIs was showed in other cancer types, there was no ICIs treatment cohort of CC or HNSCC included for clinical analysis, making the biomarker role of LRP1B only focus on cancer survival, mutation count, AUC analysis, and molecular bases of CC and HNSCC." (PMID 33994859, 2021). "Although no literature exists regarding glycosylation of LRP1B in cancer, its known participation in multiple cancers suggests that altered glycosylation of the protein could affect the course of the disease." (PMID 29531238, 2018).
adenocarcinoma (5 papers, 2021 to 2025). A common cancer characterized by the presence of malignant glandular cells. "The other genes that were much more mutated in SCC (with estimated mutation proportion in SCC and in adenocarcinoma, respectively) were LRP1B (23%, 10%), KMT2D (16%, 7%), FAT1 (15%, 5%), CDKN2A (12%, 2%), NOTCH1 (10%, 3%), and NFE2L2 (10% and 1%)." (PMID 34645806, 2021). "LRP1B mutation has been associated with increased immune cell infiltration and elevated expression of immune-related genes in NSCLC patients with adenocarcinoma treated with ICB, suggesting a possible role in the improved response to ICB." (PMID 40011914, 2025).
colon (2 papers, 2022). "On the other hand, KRAS was mutually exclusive with LRP1B in the left-side colon tumors, while the result was not significant in other sites." (PMID 36439454, 2022).
hematologic malignancies (1 paper, 2025).
neurodegenerative disease (1 paper, 2024). A disorder of the central nervous system characterized by gradual and progressive loss of neural tissue and neurologic function.
LRP1B also shares sentences with these, for which no sentence is quoted: lung squamous cell carcinoma (5 papers); esophageal cancer (4); stomach cancer (4); oral squamous cell carcinoma (3); renal carcinoma (3); adenoma (2); coronary aneurysm (2); esophagogastric junction adenocarcinoma (2); medulloblastoma (2); schizophrenia (2); serous ovarian cancer (2); small cell lung carcinoma (2); stomach adenocarcinoma (2); acute myeloid leukemia (1); amyloidosis (1); Anorexia (1); asthma (1); benign neoplasm (1); brain neoplasm (1); bronchioloalveolar carcinoma (1); buccal mucosa cancers (1); cervical adenocarcinoma (1); Chordoid Meningioma (1); chronic lymphatic leukemia (1); chronic myeloid leukemia (1); clear cell carcinoma (1); colon adenocarcinoma (1); endometrial cancer (1); follicular lymphoma (1); hairy cell leukemia (1).
A further 30 diseases each share a sentence with LRP1B in 1 paper.